NUP160 (nucleoporin 160)
Description:
Functions as a component of the nuclear pore complex (NPC). Involved in poly(A)+ RNA transport.
Synonyms: KIAA0197; FLJ22583; NPHS19
Tractability: PROTAC: ubiquitination databases record sites on it; its protein half-life has been measured.
Gene: Protein-coding gene on chromosome 11 (47,778,087 to 47,848,557, reverse strand). Ensembl gene ENSG00000030066.
Subcellular location: Nucleus, nuclear pore complex
Pathways (Reactome):
Disease: Defective TPR may confer susceptibility towards thyroid papillary carcinoma (TPC); HCMV Early Events; HCMV Late Events; NEP/NS2 Interacts with the Cellular Export Machinery; NS1 Mediated Effects on Host Pathways; Nuclear import of Rev protein; Rev-mediated nuclear export of HIV RNA; SARS-CoV-2 activates/modulates innate and adaptive immune responses; Transport of Ribonucleoproteins into the Host Nucleus; Viral Messenger RNA Synthesis; Vpr-mediated nuclear import of PICs
Cell Cycle: Amplification of signal from unattached kinetochores via a MAD2 inhibitory signal; EML4 and NUDC in mitotic spindle formation; Mitotic Prometaphase; Nuclear Pore Complex (NPC) Disassembly; Postmitotic nuclear pore complex (NPC) reformation; Resolution of Sister Chromatid Cohesion; Separation of Sister Chromatids
Metabolism of RNA: Transport of Mature mRNA Derived from an Intronless Transcript; Transport of Mature mRNA derived from an Intron-Containing Transcript; Transport of the SLBP Dependant Mature mRNA; Transport of the SLBP independent Mature mRNA; snRNP Assembly; tRNA processing in the nucleus
Metabolism of proteins: SUMOylation of DNA damage response and repair proteins; SUMOylation of DNA replication proteins; SUMOylation of RNA binding proteins; SUMOylation of SUMOylation proteins; SUMOylation of chromatin organization proteins; SUMOylation of ubiquitinylation proteins
Metabolism: IP3 and IP4 transport between cytosol and nucleus; IP6 and IP7 transport between cytosol and nucleus; IPs transport between nucleus and cytosol; Regulation of Glucokinase by Glucokinase Regulatory Protein
Cellular responses to stimuli: Regulation of HSF1-mediated heat shock response
Immune System: ISG15 antiviral mechanism
Signal Transduction: RHO GTPases Activate Formins
Gene Ontology:
Molecular function: protein binding; structural constituent of nuclear pore
Biological process: mRNA export from nucleus; nephron development; nucleocytoplasmic transport; intercellular transport
Cellular component: kinetochore; nuclear envelope; nuclear pore; nuclear pore outer ring; cytosol
Genetic constraint (gnomAD): Loss-of-function variants: 47 observed, 100.66 expected, observed/expected ratio (o/e) 0.47, 90% interval 0.37 to 0.6. The upper end of that interval is the gene's LOEUF score, 0.6, which puts it in group 2 of 6, group 1 being the genes least tolerant of losing a copy. Missense variants: 1,087 observed, 1,190.5 expected, observed/expected ratio (o/e) 0.91, 90% interval 0.87 to 0.96. Synonymous variants: 413 observed, 437.7 expected, observed/expected ratio (o/e) 0.94, 90% interval 0.87 to 1.02.
Homologues: Orthologues: chimpanzee NUP160 (99% identical), macaque NUP160 (99% identical), pig NUP160 (95% identical), rabbit NUP160 (94% identical), rat Nup160 (93% identical), mouse Nup160 (93% identical), dog NUP160 (92% identical), guinea pig NUP160 (87% identical), tropical clawed frog nup160 (70% identical), zebrafish nup160 (52% identical), Drosophila melanogaster Nup160 (29% identical), Caenorhabditis elegans npp-6 (18% identical).
Diseases named in the same sentence as NUP160 in open-access papers:
NUP160 is named in the same sentence as 19 diseases in open-access papers, as found by Europe PMC text mining. Sharing a sentence is not in itself a finding about the gene and the disease. The quoted sentences say what the papers report.
angiosarcoma (3 papers, 2017 to 2025). A malignant tumor arising from the endothelial cells of the blood vessels. "Regulation of NUP160 expression could provide therapeutic benefit in some diseases such as diabetic nephropathy, angiosarcoma, and steroid‐resistant nephrotic syndrome." (PMID 41394771, 2025).
diabetic nephropathy (3 papers, 2021 to 2025). "Interestingly, NUP160 expression was found to be upregulated, which is associated with the inhibition of autophagy and increased inflammatory response in mice with diabetic nephropathy." (PMID 37569434, 2023).
nephrotic syndrome (3 papers, 2020 to 2024). A collection of symptoms that include severe edema, proteinuria, and hypoalbuminemia; it is indicative of renal dysfunction. "Mutations in the NUP160 gene, which encodes a protein component of the nucleopore complex nucleopore 160 KD, are responsible for inducing steroid-resistant nephrotic syndrome." (PMID 34533106, 2021). "Similarly, NUP160 is a gene we had proposed as a novel candidate for steroid-resistant nephrotic syndrome based on two siblings who were compound heterozygous for missense and nonsense variants." (PMID 33456446, 2020).
Autoimmunity (2 papers, 2015 to 2017). The occurrence of an immune reaction against the organism's own cells or tissues. "For example, in the largest subunit of the NPC, 3 out of 9 putative complex members of the Nup107-160 sub-complex, i.e., MOS3/Nup96, Nup160, and Seh1, were found to be essential for the basal resistance and snc1 activated autoimmunity in Arabidopsis." (PMID 28205154, 2017).
HIV-1 infection (2 papers, 2018 to 2023). The type species of lentivirus and the etiologic agent of acquired immunodeficiency syndrome (AIDS). "As has been previously reported, Nup160 depletion affected WT and CA mutant HIV-1 infection, which is likely due to the critical role it plays in NPC formation." (PMID 37355754, 2023). "Moreover, some Nup depletions (SEH1, NUP85, NUP160, SEC13, NUP98, NUP107, ELYS/ACHTF1, NUP93, NUP205, NUP88, and NUP214) that reduced both HIV-1 infection and MX2 activity in dividing HeLa cells, affected MX2 activity but not HIV-1 infection in non-dividing HeLa cells." (PMID 30084827, 2018).
congenital heart disease (1 paper, 2024). A heart disease that is present at birth. "Previous studies have linked NUP93, NUP107 and NUP160 to cancer, congenital heart disease, neurological diseases and gonadal dysgenesis." (PMID 38650033, 2024).
diabetics (1 paper, 2023). "In particular, beta cells of diabetics exhibited decreased expression of genes encoding molecular chaperones belonging to the heat shock families Hsp70 (HSPA1B, HSPA7, and HSPA8) and Hsp90 (HSP90AA1 and HSP90AB1) as well as co-chaperones (BAG3 and ST13) and nucleoporins (NDC1, NUP160, and POM121C)." (PMID 37569434, 2023). "We also found changes in the expression of nucleoporin genes such as NDC1, NUP35, NUP58, NUP107, NUP160, and POM121C in pancreatic beta cells of patients with type 2 diabetes mellitus." (PMID 37569434, 2023).
female sterility (1 paper, 2012). "Among them, Nucleoporin 160 (Nup160) of D. simulans was identified as the gene underlying female sterility on the D. melanogaster genetic background." (PMID 22191063, 2012).
renal fibrosis (1 paper, 2021). A final common manifestation of a wide variety of chronic kidney diseases characterized by glomerulosclerosis and tubulointerstitial fibrosis. "In this study, we used HG-treated NRK-52E cells and STZ-induced DN mice to explore the function of NUP160 on autophagy and renal fibrosis in vitro and in vivo." (PMID 34533106, 2021).
Sepsis (1 paper, 2025). Sepsis is defined as life-threatening organ dysfunction caused by a dysregulated host response to infection. "Collectively, our bioinformatic and experimental findings indicate that ATP11B, RBBP7, DOCK10, and NUP160 are implicated in the pathogenesis and progression of sepsis." (PMID 41394771, 2025). "ATP11B, RBBP7, DOCK10, and NUP160 may play the major role in the occurrence and progression of sepsis." (PMID 41394771, 2025). "Nonetheless, the mRNA expression of NUP160 and DOCK10 was elevated in LPS‐induced sepsis, which contradicts the findings from the bioinformatic analysis." (PMID 41394771, 2025). "Despite the discordance in expression trends for NUP160 and DOCK10 between bioinformatic predictions and our murine validation, their potential as sepsis biomarkers cannot be dismissed." (PMID 41394771, 2025). "The mRNA expression of NUP160 and DOCK10 was elevated in LPS‐induced sepsis, although the bioinformatic analysis indicated a contrary trend." (PMID 41394771, 2025). "However, the mRNA expression of NUP160 and DOCK10 was upregulated in LPS‐induced sepsis, which was contrary to the bioinformatic analysis results." (PMID 41394771, 2025).
viral infections (1 paper, 2021).
neurodegenerative disease (2 papers, 2016 to 2018). A disorder of the central nervous system characterized by gradual and progressive loss of neural tissue and neurologic function. "Age-related defects in NUP160 and the nuclear pore complex has been proposed to contribute to abnormal protein trafficking, and in turn to neurodegenerative diseases." (PMID 26919393, 2016).
neurological diseases (2 papers, 2021 to 2024). "Besides that, in this LD block, several variants act as eQTLs/sQTLs in the brain and whole blood, altering the expression of many genes already related to LOAD or other neurological diseases in human or animal studies, such as CELF1 itself, MADD, MYBPC3, NR1H3, NUP160, SPI1, and TOMM40." (PMID 34291080, 2021).
heart (1 paper, 2012). "This study shows alterations in specific proteins (NDC1, Nup160, Nup153 and Nup93) that compose NPC in ischaemic and dilated human heart." (PMID 23152829, 2012).
infection (1 paper, 2018). The state of being infected such as from the introduction of a foreign agent such as serum, vaccine, antigenic substance or organism. "FIV infectivity and MX2 resistance were also unaffected by most Nup depletions in HT1080 cells, but a small number of knockdowns (NUP93, NUP205, NUP160) were significantly deleterious to FIV infection in HOS cells." (PMID 30084827, 2018).
tumor (1 paper, 2022). "Moreover, C18orf25, NUP160, DYNC1LI2, SYNJ1, MAPK1, and CLOCK were lowly expressed in tumor tissues." (PMID 36249009, 2022).
NUP160 also shares sentences with these, for which no sentence is quoted: cancer (2 papers); Alzheimer disease (1); type 2 diabetes mellitus (1).